CATIP (ciliogenesis associated TTC17 interacting protein)
Description:
Plays a role in primary ciliogenesis by modulating actin polymerization.
Synonyms: C2orf62; MGC50811
Tractability: Antibody: UniProt places it where antibodies can reach, with high confidence; its Gene Ontology location is reachable by antibodies, with high confidence.
Gene: Protein-coding gene on chromosome 2 (218,356,857 to 218,369,962, forward strand). Ensembl gene ENSG00000158428.
Subcellular location: Nucleus; Cytoplasm; Cell membrane; Cytoplasm, cytoskeleton
Subcellular location (Human Protein Atlas): Connecting piece; Mid piece
Gene Ontology:
Molecular function: protein binding
Biological process: actin filament polymerization; cilium organization
Cellular component: actin cytoskeleton; cytoplasm; nucleus; plasma membrane; cytoskeleton
Genetic constraint (gnomAD): Loss-of-function variants: 36 observed, 41.54 expected, observed/expected ratio (o/e) 0.87, 90% interval 0.66 to 1.14. The upper end of that interval is the gene's LOEUF score, 1.14, which puts it in group 5 of 6, group 1 being the genes least tolerant of losing a copy. Missense variants: 470 observed, 485.72 expected, observed/expected ratio (o/e) 0.97, 90% interval 0.9 to 1.04. Synonymous variants: 213 observed, 201.42 expected, observed/expected ratio (o/e) 1.06, 90% interval 0.94 to 1.18.
Homologues: Orthologues: macaque CATIP (96% identical), chimpanzee CATIP (88% identical), pig CATIP (79% identical), dog CATIP (75% identical), rat Catip (74% identical), mouse Catip (72% identical), guinea pig CATIP (68% identical), rabbit CATIP (59% identical), tropical clawed frog catip (41% identical), zebrafish catip (37% identical). Paralogues in human: BAMBI (12% identical).
Diseases named in the same sentence as CATIP in open-access papers:
CATIP is named in the same sentence as 2 diseases in open-access papers, as found by Europe PMC text mining. Sharing a sentence is not in itself a finding about the gene and the disease. The quoted sentences say what the papers report.
Infertility (1 paper, 2024). "Alternatively, genes with no reported COI are enriched in gene sets associated with germ cell development and implicated in infertility mainly caused by spermatogenic failure (e.g., CATIP, CFAP65, CEP19) and oocyte/zygote/embryo maturation arrest (e.g., PADI6, REC114, WEE2)." (PMID 39202055, 2024).
CATIP also shares sentences with these, for which no sentence is quoted: ciliopathies (1 paper).